EGFR (epidermal growth factor receptor)
Diseases named in the same sentence as EGFR in open-access papers (continued):
Sharing a sentence is not in itself a finding about the gene and the disease.
tumor (continued). "Wnt and EGFR pathways have been reported to closely interact in tumorigenesis, but how they cross-talk and co-activate tumor progression remains an unanswered, interesting topic." (PMID 20828404, 2010). "Experimental results have also indicated the need to better understand the interaction of EGFR with other family members, signaling events, and the tumor environment in ovarian as well as in other cancers." (PMID 20037743, 2010). "The HR for OS according to patients, clinical subgroups, tumor, and blood marker subgroups was near 1.0, with exception of EGFR gene amplification (HR of 0.48)." (PMID 20433767, 2010). "In some cancers, tumor formation is dependent on aberrant expression of epidermal growth factor receptor (EGFR), which serves as an antigenic target for cetuximab and panitumumab." (PMID 20936120, 2010). "In a tumor of three different histologies (squamous cell, adenocarcinoma and neuroendocrine cells) and aggressive in behavior, we investigated the EGFR copy number by fluorescence in situ hybridization (FISH) in each component of the tumor." (PMID 20961443, 2010). "The results in this paper showed that human TGFα-derived TGFαL3 is capable of directing SAgs to tumours and exerting an inhibitory effect on tumour growth, which makes TGFαL3SEAD227A an attractive candidate for immunotherapy on EGFR-expressing tumours." (PMID 21176167, 2010). "EGFR has been attributed an important role in carcinogenesis of several tumor types and EGFR inhibitors are currently used in treatment of some of them." (PMID 20565817, 2010). "According to the criteria that samples with more than 10% of tumor cells showing membranous staining of any intensity should be considered as EGFR IHC-positive, 114 cases were IHC-positive and 19 cases were IHC-negative." (PMID 20637128, 2010). "Activated STAT1, STAT3 and STAT5 are often observed in solid and liquid tumors, and are required for tumor transformation and progression which involves a set of oncogenes such as EGFR, Ras, Src, and FAK." (PMID 20576130, 2010). "Downregulation of EGFR, increased apoptosis, dephosphorylation of ErbB4 at tyrosine 1284 site and downregulation of EGFR target genes cyclin D1 and c-myc played a major role in tumor inhibition." (PMID 27713315, 2010). "In intestinal tumor cells, APC and KRAS, a downstream target of EGFR signaling, act synergistically in enhancing Wnt signaling, tumor formation and progression." (PMID 20828404, 2010). "Poor/undifferentiated tumours had significantly higher EGFR intensity compared with tumours with well/moderate histological grade (P=0.007) (data not shown)." (PMID 19997103, 2010). "TGF-α was also shown to increase proliferation as measured by [3H]thymidine incorporation as well as increase levels of the tumor markers cancer antigen-125 and tissue polypeptide antigen in EGFR-positive primary human serous ovarian cancer cells." (PMID 20037743, 2010). "The aim of this study is to investigate the correlation between the expression of EGFR in tumor tissue and peripheral blood in non-small cell lung cancer (NSCLC) patients." (PMID 21159244, 2010). "In 22 tumor tissues with wt EGFR, we found high expression of EGFR (D38B1) protein (score 2 or 3) in 8 cases (36%) and weak positivity (score 1) in 4 cases (18%)." (PMID 21167064, 2010). "EGFR was expressed by terminal duct epithelial cells, gland alveolus cells and tumor cells, as well as some mesenchymal cells." (PMID 20092659, 2010). "The EGFR mRNA and protein expression levels in vitro and in tumor lysates from mouse xenografts were lower in 1Cc8 when compared to SCC1." (PMID 20856931, 2010). "Overall, 42 tumour blocks or slides were available for EGFR analysis and were reviewed centrally at the Institute of Pathology, Technische Universität München." (PMID 20068568, 2010). "Since activation of epidermal growth factor receptor (EGFR) promotes mechanisms leading to tumor growth and progression, EGFR-targeted agents are being widely explored." (PMID 20459769, 2010).
tumor (continued). "Using an EGFR antibody, we evaluated the range of expression seen in CTCs isolated from tumor-cell spike-in blood samples from four of the eight cell lines." (PMID 20838621, 2010). "Cancer cell distinguishes itself from the normal cell by expressing proteins or receptor on the cell surface, imaging of such surface proteins such as EGFR has been studied to track the tumor progression or even monitor tumor response to treatment." (PMID 20711449, 2010). "In cancerous cells, EGFR pathway activation results in cell proliferation, inhibition of apoptosis, activation of invasion, metastasis and tumour neovascularisation." (PMID 21139621, 2010). "We found that tumours co-expressing phospho-EGFR and EGFR had a similar clinical outcome as those expressing EGFR alone." (PMID 19997103, 2010). "Patients whose tumours were analysed for phospho-EGFR had a median age of 64 years (mean 62.5, range 26–85)." (PMID 19997103, 2010). "Epidermal growth factor receptor (EGFR) kinase domain mutations hyperactivate the kinase and confer kinase addiction of the non-small-cell lung cancer (NSCLC) tumor cells." (PMID 20459863, 2010). "First, LeY structure was found being contained within the epidermal growth factor receptor (EGFR) on the surface of tumor cells and to participate in EGFR signaling." (PMID 21152298, 2010). "These included monoclonal antibodies directed against major tumor antigens, including EGFR, Her2/neu and prostate-specific membrane antigen (PSMA), which successfully mediated CAR-independent cell transduction." (PMID 21994621, 2010). "To date, several clinical trials have been carried out to identify the molecular characteristics of the tumours predictive of response to EGFR antagonists." (PMID 20664595, 2010). "EGFR activation leads to receptor tyrosine-kinase activation and activation of a series of downstream signaling activities that mediate tumor cell proliferation, migration, invasion, and the suppression of apoptosis." (PMID 24281220, 2010). "In this model, cancers that are dependent on critical oncogenic pathways, like the EGFR pathway for tumor cellular maintenance, undergo an exaggerated/prolonged apoptosis relative to wild type tumor cells when exposed to the same cytotoxic agents." (PMID 20942962, 2010). "Using this approach, high affinity conjugation of human monoclonal antibodies to the tumor marker epidermal growth factor receptor (EGFR), CD40 and CD40L, have been shown to result in infectivity enhancement in cells which express the cognate target receptor." (PMID 21994621, 2010). "The gene expression signatures observed in this study seem to be mainly driven by the tumor grade, even more so than by EGFR protein expression detected by IHC and other clinical parameters." (PMID 20196851, 2010). "The cytoplasmic EGFR pathway often leads to tumorigenesis, tumor proliferation, metastasis, chemoresistance and radioresistance through the activation of Ras, PI-3K and STATs." (PMID 20092659, 2010). "The concept of chemosensitization by EGFR blockade was provided by studies utilizing EGFR-blocking antibodies in combination with cisplatin or doxorubicin in human tumor xenografts." (PMID 20064265, 2010). "The amounts of CCR7 (Figure 1B2) and EGFR (Figure 1E2) were detected in 82% and 66% of tumor cells, respectively, in the cytoplasm and/or membrane." (PMID 20181250, 2010). "The expressions of VEGF-C mRNA and EGFR mRNA were detected in tumor tissues and lymph node tissues by reverse transcription polymerase chain reaction (RT-PCR) and real-time fluorescence quantitative PCR." (PMID 21159248, 2010). "Within this model, substituting the number of metastatic lymph nodes for tumour stage yielded similar results for EGFR intensity." (PMID 19997103, 2010). "The imprinted gene decorin and the oncogene EGFR were down-regulated in tumor tissues, while the oncogene cyclin D1 was up-regulated." (PMID 20092659, 2010).
tumor (continued). "EGFR is over-expressed in MMe and this correlates significantly with increased tumor cell proliferation and with the promotion of angiogenesis." (PMID 21124760, 2010). "For instance, the efficacy of epidermal growth factor receptor (EGFR) antagonists has been shown to depend on expression of its target -EGFR- in the tumor." (PMID 20421987, 2010). "Blockade of EGFR also inhibited G3 effects on tumor cell chemotactic migration to bone stromal cells; while inhibition of EGFR and ERK did not significantly influence G3's effect on cell attachment." (PMID 21079779, 2010). "The number of genes co-amplified with the EGFR gene thus ranges from 2 (tumour 22) to 12 (tumour 4)." (PMID 21170331, 2010). "In tumor cells, there was elevated EGFR immunoreactivity in most samples, decreased membranous staining and increased cytoplasmic/nuclear staining of β-catenin, and positive staining for cyclin D1." (PMID 20302655, 2010). "It is known that the cadherin receptor family, integrin receptor family, and activation of EGFR all play a role in promoting anchorage-independent survival and spread of tumor cells." (PMID 20074345, 2010). "Epidermal growth factor receptor is a member of the ErbB family of transmembrane receptor tyrosine kinases that have a crucial role in tumour cell proliferation, survival, adhesion, migration, and differentiation." (PMID 19935793, 2010). "Due to its easier application, we used the criterion that samples with more than 10% of tumor cells showing membranous staining at levels 2+ and 3+ should be considered to be EGFR IHC-positive in our following analysis." (PMID 20637128, 2010). "The analysis of our results showed that the intensity of EGFR tumor expression (IHC score 2-3 vs 0-1) was significantly related to a prolonged PFS." (PMID 20398370, 2010). "Assessment of EGFR gene amplification was performed by fluorescence in situ hybridization (FISH) testing of the tumor specimen using the EGFR-CEP (chromosome 7 centromere) dual color DNA probe (performed by Genzyme Genetics)." (PMID 20961434, 2010). "In this study, we examined the cellular localization of EGFR in RCC tumor portion and normal-looking renal cortical tissue from the same patient." (PMID 19747398, 2009). "For instance, human pancreatic xenografts treated with a combination of the EGFR monoclonal antibody cetuximab and A-928605 results in an additive effect on tumor growth inhibition when compared to either of these agents dosed as monotherapies." (PMID 19732452, 2009). "Among other molecular cofactors investigated, epidermal growth factor (EGF) receptor (EGFR) overexpression is frequent in CC and is an independent predictor of poor prognosis in advanced stage tumours." (PMID 19654571, 2009). "• anti-EGFR targeted therapy improves locoregional control and overall survival in combination with radiotherapy in locally advanced tumours." (PMID 19828033, 2009). "C-myc and EGFR appeared central in many aspects of carcinogenesis, tumor grade, tumor invasiveness, and cancer staging." (PMID 19243595, 2009). "We extended the comparison between primary tumours and metastatic sites to the analysis of molecular markers belonging to EGFR downstream cascade, which have been previously identified as potentially predictive for anti-EGFR MoAb efficacy." (PMID 19293803, 2009). "Overall, the same pattern of EGFR protein expression between primary tumour and related metastasis, either at distant sites or in lymph nodes, was observed in all cases (κ=1, P<0.0001)." (PMID 19293803, 2009). "This article discusses the consensus outcomes of a global workshop convened to discuss key technical issues and standardise reading strategies for the EGFR FISH assay of NSCLC tumour tissue." (PMID 19861557, 2009). "MASI in its various forms is frequently present in mutant EGFR and KRAS tumor cells, and is associated with increased mutant allele transcription and gene activity." (PMID 19826477, 2009).
tumor (continued). "In contrast, EGFR cytoplasmic staining was significantly higher in normal than in tumor tissues (P < 0.001)." (PMID 19747398, 2009). "In summary, thirty-one of 32 tumor samples (97%) were found to be EGFR positive, while in 22 samples (69%) EGFR was overexpressed." (PMID 20066159, 2009). "The staining pattern of EGFR in luminal B subtype tumors was diffuse and strong, frequently intensifying at the leading edges of tumor invasion." (PMID 19442295, 2009). "Correlative data from tumor biopsies confirm that TKIs reach their molecular targets and suppress the activity of EGFR, HER2 and MAPK signaling." (PMID 19432987, 2009). "The clinical significance of over-expression of EGFR in a multitude of cancers has been heavily investigated, and many studies have reported that high expression of EGFR in tumours is a marker of poor clinical outcome." (PMID 19531065, 2009). "We characterised all available triple-negative tumours (56 of 81 (69%)) with additional morphological classification and immunohistochemical staining for CK5/6 and EGFR to determine what proportion of the triple-negative tumours had the basal-like phenotype." (PMID 19320967, 2009). "Especially EGFR is expressed in almost all HNSCC tumours, in keeping with the squamous cell phenotype, while its immunohistochemical protein staining is a subjective assay lacking the dynamic range of quantitative evaluation." (PMID 19830244, 2009). "Using secreted Gluc, we localized systemic metastases by BLI and quantitatively monitored the total viable metastatic tumor burden by blood Gluc assay during the course of treatment with lapatinib, a dual tyrosine kinase inhibitor of EGFR and HER2." (PMID 20016816, 2009). "Epidermal growth factor receptor (EGFR) plays an important role in tumor cell proliferation, differentiation and survival." (PMID 19788747, 2009). "Although ADT initially reduces tumour growth, it often results in an increased EGFR expression and subsequently increased androgen-induced growth and development of androgen-refractory tumours and metastasis." (PMID 19888222, 2009). "The aim of this study is to analyse molecular alterations predictive for anti-EGFR therapies response, such as EGFR gene status, K-Ras and BRAF mutations, and PTEN protein expression, in primary tumour and synchronous or metachronous metastasis." (PMID 19293803, 2009). "The epidermal growth factor receptor (EGFR) was anticipated to be a good drug target for SCCHN treatment because the majority of SCCHN overexpress EGFR, and higher tumor levels of EGFR are associated with poorer clinical outcomes." (PMID 19636423, 2009). "Src family kinases mediate EGFR-dependent and -independent tumor progression pathways in many cancers including SCCHN." (PMID 19636423, 2009). "Two groups of patients are therefore of particular interest: patients with Chr7 disomy in primary tumour and EGFR gene CNG in paired metastatic lesions, and patients with the opposite pattern." (PMID 19293803, 2009). "Xenogeneic EGFR gene was demonstrated to induce antigen-specific immune response against EGFR-expressing tumor with intramuscular administration." (PMID 19178753, 2009). "In general, the expression level of the phosphorylated proteins was significantly less than that of total EGFR and the signal from phosphorylated antigens was more prominent in tumor cells located toward the periphery of the tissue." (PMID 19765296, 2009). "It is this robustness feature of EGFR signaling cascades which enables signaling in tumour cells to be so resistant to anti-cancer therapeutics." (PMID 20028552, 2009). "There was a trend for untreated tumors in the EGFR tumor group (6 untreated vs. 1 treated) and for treated tumors in the PDGF group (3 untreated, 6 treated) but this was neither significant for GBM (p = 0.11) nor for all tumors (p = 0.09)." (PMID 19915670, 2009).
tumor (continued). "Our findings indicate that combining PDT and Erbitux significantly enhances the anti-tumor activity, by inhibiting EGFR expression, increasing apoptosis and by dephosphorylating essential EGFR tyrosine sites." (PMID 19878607, 2009). "Cetuximab, an antibody against epidermal growth factor receptor, seems also to influence long-term tumour control by affecting DNA damage repair." (PMID 19860913, 2009). "Erbitux (cetuximab), a chimeric human-murine monoclonal antibody, competitively binds to the accessible extracellular domain of EGFR and inhibits dimerisation and subsequently inhibits cell proliferation, tumor growth and metastasis." (PMID 19878607, 2009). "Considering their very diverse effects on the behaviour of EGFR, it is of great importance to investigate which combinations of EGFR ligands are expressed by a tumour." (PMID 19531065, 2009). "Maximum EGFR tumor cell membrane staining of 21-24% (EGFR score 3) was noticed in the untreated tumors." (PMID 19878607, 2009). "At the same time, several proliferative pathways were elevated in the BALBLps-d mice (e.g. EGFR), further increasing the chance of tumor growth and progression." (PMID 19925653, 2009). "In fact, in patients with differences between primary tumour and related distant metastasis, the EGFR gene status pattern observed in lymph nodes was superimposable to primary tumours in six cases and to distant metastasis in two cases." (PMID 19293803, 2009). "This clinical breakthrough makes imperative the need for the identification of biomarkers that would predict tumour response or resistance to EGFR-modulating agents." (PMID 19830244, 2009). "Studies show that antibodies that block the EGF binding site of EGFR inhibit tumor cell proliferation." (PMID 19878607, 2009). "It previously has been shown that regulation of Cav-1 plays a central role in the complex cellular changes leading to metastasis via epithelial-to-mesenchymal transition in human tumor cells overexpressing EGFR." (PMID 19239691, 2009). "EGFR heterodimerization with ErbB2, as is often observed in tumor cells, has also been shown to impair lysosomal degradation of EGFR apparently due to increased recycling and/or reduced internalization." (PMID 19948031, 2009). "The ability of A-928605 to significantly inhibit growth in the SK-N-FI model as a single agent led to the analysis of this agent in other human tumor models in combination with clinically approved therapeutics targeting EGFR." (PMID 19732452, 2009). "Positive immunostaining was observed in 6.2–72.6% (median 35%) of tumours, and in 7 studies (63.6%) EGFR expression predicted poor overall survival." (PMID 19513073, 2009). "Expression of EGFR, “a survival factor for tumor cells”, is even considered to be necessary to maintain KCs in a proliferative state." (PMID 19551138, 2009). "Meanwhile, the radiation-induced apoptosis of tumor cells was increased by inhibition of the EGFR through up-regulation of PTEN." (PMID 19723324, 2009). "Tumor tissue from a subgroup of these patients was analyzed by immunohistochemistry to measure the expression level of EGFR and four activated (phosphorylated) members of the pathway, pEGFR, pERK, pAKT, and pSTAT3." (PMID 19765296, 2009). "On the other hand, tumours in mice treated with cetuximab exhibited a complete abrogation in the levels of phosphorylation of EGFR and ERK even when the antibody was administered as a single agent." (PMID 19293809, 2009). "A-928605 is also efficacious in tumor models when used in combination with clinically approved therapeutics designed against EGFR." (PMID 19732452, 2009). "Our data, demonstrating different deregulation mechanisms of the EGFR pathways between primary tumours and related metastasis, deserve confirmation in larger and prospective studies." (PMID 19293803, 2009). "The epidermal growth factor receptor (EGFR) signalling pathway has an important function in tumour development and progression." (PMID 19277036, 2009).